CHD8 (chromodomain helicase DNA binding protein 8)
Diseases named in the same sentence as CHD8 in open-access papers (continued):
Sharing a sentence is not in itself a finding about the gene and the disease.
autism (continued). "The gene encoding chromodomain helicase DNA-binding protein 8 (CHD8), an ATP-dependent chromatin remodeling factor that regulates gene transcription, has been described as an autism susceptibility/intellectual disability gene, as mutations in CHD8 were found to be strongly associated with ASD1–6." (PMID 36878905, 2023). "Although studies have shown that BTBR mice share important changes in relevant genes and proteins involved with autism, additional studies in mice carrying mutations in specific genes involved in autism (ex, CHD8, Shank3) are necessary to recognize the impact of early anesthetic exposures in NDDs." (PMID 34912193, 2021). "This is considerably higher than most other autism-associated genes, which suggests that CHD8 mutations may often be enough to induce the autism phenotype." (PMID 34440307, 2021). "Chromodomain Helicase DNA-binding 8 (CHD8) is a high confidence risk factor for autism spectrum disorders (ASDs) and the genetic cause of a distinct neurodevelopmental syndrome with the core symptoms of autism, macrocephaly, and facial dysmorphism." (PMID 33477995, 2021). "CHD8 has direct effects on biological pathways that have previously been implicated in autism." (PMID 34440307, 2021). "This is not surprising since it is well documented that de novo mutations, including germinal and postzygotic mutations, are important players in the genetic architecture of neurodevelopmental disorders, and specifically involving CHDs de novo mutations in CHD8 have been recurrently found in autism." (PMID 34828433, 2021). "In addition, PAK2/Pak within 3q29, TBX1/org-1 within 22q11.2, autism-associated CHD8/kis, and microcephaly-associated ASPM/asp also showed smaller wing areas and vein lengths." (PMID 32579612, 2020). "CHD8 (Chromodomain Helicase DNA Binding Protein 8) codes for a DNA helicase that suppresses gene expression by affecting chromatin restructure, and is a significant contributor to autism susceptibility and CHARGE syndrome (a congenital deaf–blindness syndrome) through its interaction with CHD7." (PMID 31078131, 2019). "We therefore expected Chd8+/− mice to present with robust, autism-associated behaviors." (PMID 29668850, 2018). "BAPQ data for all three CHD8 carriers suggests that parents carrying CHD8 LGD mutations show autistic traits with high scores across the domains of autism: behavior (rigid personality) and social communication (pragmatic language deficits)." (PMID 30564305, 2018). "By characterizing Treg-specific CHD8 knockout (KO) mouse models, we found that loss of CHD8 dampened Treg fitness, which was associated with genetic and epigenetic alterations, leading to early, fatal, effector T cell-mediated inflammation, offering an explanation for the immune disorders in autism." (PMID 40155813, 2025). "In addition to the core behavioral symptoms of autism, affected individuals frequently present with gastrointestinal symptoms that are also common among individuals harboring mutations in the gene encoding CHD8." (PMID 37783686, 2023). "CHD8 is an autism‐associated protein and may represent a specific genetic subtype of autism." (PMID 38818219, 2022). "Interestingly, patients with mutations in the autism risk gene CHD8 show defects in sleep initiation and maintenance, and mutation of the D. melanogaster ortholog kismet disrupts sleep architecture and increases serotonin labeling of the gut during development." (PMID 36409783, 2022). "In support of these early observations, integrated analysis of 15 patients with disruptive CHD8 mutation (13 de novo, one inherited, and one of unknown origin) revealed that autism was the most common diagnosis (N =13) closely followed by macrocephaly (N = 12)." (PMID 33477995, 2021). "The central role of CHD8 in neurodevelopment highlights its importance in understanding the genetic basis of autism." (PMID 40981259, 2025).
autism (continued). "The WNT pathway, which includes CHD8 (an autism-related chromatin modifier) and beta-catenin, has long been implicated in ASD pathogenesis." (PMID 38525876, 2024). "Another aspect of this study is that it highlights the relationship between the autism gene Chd8 and infertility." (PMID 38224953, 2024). "Many genes are associated with autism spectrum disorders, and copy number variations and rare gene mutations (e.g., SHANK3, NRXN1, CHD8, SCN2A) are closely linked to autism." (PMID 39734494, 2024). "The CHD8 gene is a high-confidence risk factor for ASD and a genetic cause of a distinct neurodevelopmental syndrome with core symptoms of autism, macrocephaly, and facial dysmorphia (OMIM # 615032)." (PMID 39685474, 2024). "A combination of zebrafish and transcriptomic analyses revealed the role of the autism-candidate chd8 in the development of the enteric nervous system, serotonin metabolism, and intestinal integrity." (PMID 36375841, 2023). "Taking our data together, we propose a causal developmental link between chd8, impairment of the NCC development, dysregulation of the serotonergic pathway, alterations of the intestinal and immune homeostasis, and autism-associated GI complaints." (PMID 36375841, 2023). "The present study sought to explore the relationship between CHD8 haploinsufficiency and GI dysfunction in mice, while also exploring the potential link between these factors and autism-related behavioral phenotypes." (PMID 37783686, 2023). "Our findings propose a causal developmental link between chd8, NCC development, intestinal homeostasis, and autism-associated gastrointestinal complaints." (PMID 36375841, 2023). "The expression analysis of overlapping autism genes revealed that CHD8 is required for their active transcription; therefore, majority of these genes are upregulated in CHD8 KO." (PMID 36575212, 2022). "Our findings further predict enlargement of the neural progenitor pool in CHD8+/− developing brains, providing a mechanistic basis for macrocephaly in this autism subtype." (PMID 36222238, 2022). "CHD8, a major autism gene, functions in chromatin remodelling and has various roles involving several biological pathways." (PMID 36182950, 2022). "Collectively, our findings provide compelling evidence for dysregulated proliferation of neural progenitors in CHD8+/− developing brains and strengthen the unexpected connection between autism and cancer." (PMID 36222238, 2022). "Haploinsufficient Chd8 mice exhibited an autism-like phenotype including typical autistic behavior, macrocephaly, and craniofacial abnormalities similar to ASD individuals." (PMID 34440307, 2021). "Following this, we reconsider present evidence for CHD8 as a high confidence risk factor for ASD and as a genetic cause of a distinct neurodevelopmental syndrome highly associated with autism." (PMID 33477995, 2021). "The overlap of our data with DEGs from organoids engineered to knockdown CHD8, a top autism gene is also apparent." (PMID 34433918, 2021). "The literature selection process for this review was conducted in the databank PubMed via combinations of the search terms “CHD8”, “autism”, “single-cell sequencing” and “excitation inhibition balance” with date limits from January 2011 to January 2021." (PMID 33806835, 2021). "Different CHD8 mutant mouse models were developed to determine autism-like phenotypes and to fully understand their mechanisms." (PMID 34440307, 2021). "Indeed, mutations in the chromodomain helicase DNA binding protein 8 gene, one of the most commonly reported mutations in autism, have been associated with reduced axon and dendritic growth in humans, resulting in neuronal deficits that can contribute to autism pathophysiology." (PMID 34193257, 2021). "This is consistent with several previously published mouse models related to autism, including Chd8+/−, 22q11.2, Fmr1, Itgb3, En2, Nrxn1a, and Shank3." (PMID 33757588, 2021).
autism (continued). "Considering the central role of CHD8 in the genetics of autism, a deeper understanding of the physiological functions of CHD8 is important to understand the development of the autism phenotype and potential therapeutic targets." (PMID 34440307, 2021). "Strong candidate genes such as CHD8, POGZ and DYRK1A were previously reported to be associated with not only autism but also gastrointestinal issues, facial dysmorpisms, visual and feeding problems." (PMID 33338084, 2020). "Mutations in chromodomain helicase DNA-binding protein 8 (CHD8) gene, have been associated with autism, macrocephaly, speech delay, distinct facial features, sleep and gastrointestinal disturbances." (PMID 32309624, 2020). "Similar to CHD8, the single parent carrying KMT5B LGD mutations also shows a lower IQ within normal range and features consistent with a broader autism phenotype." (PMID 30564305, 2018). "For example, one study has shown that a heterozygous knockout of the autism candidate gene Chd8 led to an increase in dysregulated long gene expression, while another study found many ASD candidate genes are long genes." (PMID 29090078, 2017). "Rare mutations in other autism related genes such as CNTNAP2 and CHD8 are also associated with both autism and macrocephaly,while mutations in the risk genes AUTS2 and DHCR7 give rise to autism and microcephaly." (PMID 26076356, 2015). "Nevertheless, the activities of CHD8 in autism-relevant cell types are still poorly understood." (PMID 40104050, 2025). "While a handful of genes have been associated with DM—including known autism genes impacting cell cycle and proliferation during embryonic development (e.g., CHD8 and PTEN)—mutations of known candidate genes make up only 3% of megalencephaly in autism probands." (PMID 39887636, 2025). "In this study, we aimed to investigate whether CHD8 in Tregs affected Treg behaviors to implicate its role in immune changes in autism." (PMID 40155813, 2025). "Despite shared associations with autism and intellectual disability, disruptive variants in ADNP, CHD8, and DYRK1A may yield variable psychiatric phenotypes among children and adolescents." (PMID 38622540, 2024). "Based on the common molecular function of CHD8, future therapeutic options for autism could also be applicable as infertility treatments, and vice versa." (PMID 38224953, 2024). "Cacna2d3, Chd8, and Tbr1 are associated with autism and ID generally but not with any named syndromes." (PMID 39431203, 2024). "Our data suggest that ADNP, CHD8, and DYRK1A groups may have separable and distinct phenotypes with regard to mental health, despite their shared associations with autism and intellectual disability." (PMID 38622540, 2024). "Comorbid biomarkers may blur diagnostic boundaries, whereas autism-specific biomarkers—such as mutations in SHANK3, NRXN1, and CHD8—are directly tied to autism, but may also be found in other conditions like intellectual disabilities and ADHD." (PMID 39734494, 2024). "Together, these results suggest Chd8 as a key determinant of autism-related gastrointestinal deficits, while also laying the ground for future studies on the link between GI deficits and autism-related behaviors." (PMID 37783686, 2023). "Numerous studies proposed that CHD8 regulates the expression of autism risk genes in neural and non-neural cells raising the question of how CHD8 specifically affects neurons and how its absence can cause a common neuropsychiatric disorder." (PMID 36575212, 2022). "In this review, we discuss recent progress on the role of CHD8 in autism and neurodevelopment." (PMID 33477995, 2021).
autism (continued). "Moreover, we show how failure to control for litter-to-litter variation can mask a phenotype in Chd8V986*/+ mice that model haploinsufficiency of CHD8, a high-confidence autism gene." (PMID 33397279, 2021). "Because many of our mouse mutants with reduced CHD8 function die shortly after birth, it is not possible to fully determine to what extent reduced CHD8 function results in autism-associated behaviours in mice." (PMID 33627187, 2021). "CHD8 mutations have been previously associated with ASD schizophrenia in adults and different gastric or colorectal cancers, which indicates its relation to schizophrenia and autism at the gene level." (PMID 32309624, 2020). "It has been also reported that autism gene CHD8 modifies the expression of ZNF132." (PMID 31455857, 2020). "A study of balanced chromosomal abnormality in autism revealed disruption of genes including CHD8." (PMID 29888248, 2018). "In addition, they showed a significant enrichment of autism-candidate genes among genes with correlated temporal patterns to CHD8 in the BrainSpan atlas." (PMID 27909802, 2017). "To address these questions we utilized two resources: representative human neurodevelopmental tissues in which CHD8 gene targets can be mapped or CHD8 expression perturbed; and uniformly defined sets of ASD risk genes to query sets of CHD8 gene targets for autism risk." (PMID 25752243, 2015). "We therefore posed three questions regarding CHD8 function and its relevance to autism." (PMID 25752243, 2015). "Our findings suggest that CHD8 plays an important role in maintaining Treg fitness through genetic and epigenetic mechanisms to control autoimmunity, which may have important implications in immune changes in autism." (PMID 40155813, 2025). "Despite shared associations with autism and intellectual disability, data presented here suggest ADNP, CHD8, and DYRK1A may yield variable psychiatric phenotypes among affected children and adolescents, including differential associations with early development." (PMID 38622540, 2024). "Finally, we revealed CHD8 regulates a distinct group of autism genes positively correlated in expression patterns in the developing human cortex, suggesting a conserved and developmentally regulated transcriptional connectivity between CHD8 and its targets." (PMID 36575212, 2022). "In addition, in chromodomain-helicase-DNA-binding protein 8 (Chd8) conditional knockout mice where Chd8 is specifically ablated in oligodendrocyte lineage cells, autism-like behavioral changes appeared to correlate with myelin microstructural changes in the striatum." (PMID 34483844, 2021). "However, the role of CHD8 in neural differentiation and the mechanism of CHD8 in autism remains unclear, despite there are a few studies based on the CHD8 haploinsufficient models." (PMID 34686651, 2021). "A small blood EWAS performed in 52 cases of autism of heterogeneous etiology, nine carriers of 16p11.2del, seven carriers of pathogenic variants in CHD8, and matched controls found that DNAm patterns did not clearly distinguish autism of the heterogeneous etiology from controls." (PMID 33634770, 2021). "However, since 50% of cases with CHD8 mutations did not display autism, this suggests additional genetic or environmental factors." (PMID 34440307, 2021). "Finally, we consider continuing challenges for translational animal studies and how pluripotent stem cell-derived models could advance insight into the role of CHD8 in autism." (PMID 33477995, 2021). "Moreover, significant enrichment of autism genes was observed in CHD8-correlated genes." (PMID 31655213, 2019). "We identified subsets of overlapping DEGs in comparisons with studies involving idiopathic autism cases vs. controls (26 shared DEGs), syndromic ASD involving macrocephaly (31 shared DEGs), and modeling of mutation of the syndromic ASD gene CHD8 (32 shared DEGs)." (PMID 31893020, 2019).
autism (continued). "Given that autism is often accompanied by inflammatory disorders, including autoimmunity, and that an imbalance between T helper 17 cells (Th17) and Tregs may play a vital role in the progression of autism, it is conceivable that CHD8 impacts the immune system." (PMID 40155813, 2025). "Various genes enriched in modern humans are disease-relevant genes like CHD8 and CPEB4 in autism spectrum, HTT in Huntington’s disease, FOXP2 in language impairment." (PMID 36550402, 2022). "For seed gene pairs related to more general NDD and autism phenotypes (CHD8-CREBBP and CHD8-CTNNB1), we observe an enrichment in chromatin organization and regulation of transcription." (PMID 36699383, 2022). "Next, to further dissect the expression crosstalk between CHD8 and RAB11B/RAB11B-AS1 S/AS pair we resorted to blood transcriptomic data of the Italian Autism Network (ITAN)." (PMID 34880900, 2021). "With the recent finding of ADNP as being one of a small group of genes, including CHD8 and SHANK3 that appear to lead to autism in a substantial proportion of cases, the significance of our current results is enhanced." (PMID 28221363, 2017). "Previous CHD8 research has primarily focused on its involvement in IDDAM, which is characterized by intellectual disability, developmental regression, seizures, sleep disturbances, autism, and overgrowth." (PMID 40496977, 2025). "This suggests that the potential key role of CHD8 in VPA-induced autism is HDAC-independent, an idea that is also supported by the lack of evidence showing a relationship between maternal use of vorinostat and neonatal autism." (PMID 35073843, 2022). "CHD8 has not previously been centrally implicated in psychosis as it is associated with a congenital disorder (CHARGE syndrome) and linked to autism." (PMID 31078131, 2019).